ATG10 (autophagy related 10)
Diseases named in the same sentence as ATG10 in open-access papers (continued):
Sharing a sentence is not in itself a finding about the gene and the disease.
lung adenocarcinoma (2 papers, 2017 to 2025). A carcinoma that arises from the lung and is characterized by the presence of malignant glandular epithelial cells. "In summary, ATG5 rs510532 and ATG10 rs10036653 genetic variations in autophagy core genes are significantly associated with clinical outcomes of advanced lung adenocarcinoma treated with gefitinib." (PMID 29259263, 2017). "ATG10 rs10036653, ATG12 rs26538, ATG16L1 rs2241880 and ATG16L2 rs11235604 were significantly associated with OS of gefitinib-treated advanced lung adenocarcinoma patients (all P < 0.05)." (PMID 29259263, 2017). "We found that ATG5 rs510532 and ATG10 rs10036653 contributed to not only survival but also drug resistance among gefitinib-treated advanced lung adenocarcinoma patients." (PMID 29259263, 2017). "We found that ATG10 rs10036653, ATG12 rs26538, ATG16L1 rs2241880 and ATG16L2 rs11235604 were significantly associated with survival of lung adenocarcinoma patients (all P < 0.05)." (PMID 29259263, 2017). "Furthermore, consistent with our findings, a previous study reported that ATG-10 can be used as a promising clinical predictor in advanced lung adenocarcinoma patients for gefitinib response which is an EGFR-TKI similar to Sorafenib." (PMID 39921803, 2025).
oral mucositis (2 papers, 2019 to 2024). Inflammation of the mucous membranes of any of the structures in the mouth. "- ATG10 rs10514231 and ATG16L2 rs10898880 were significantly associated with the occurrence of grade 3–4 oral mucositis." (PMID 38473311, 2024). "Besides, we also found ATG10 rs10514231 and ATG16L2 rs10898880 were significantly associated with the occurrence of grade 3–4 oral mucositis and myelosuppression." (PMID 31692259, 2019).
acute leukemia (1 paper, 2025). A clonal (malignant) hematopoietic disorder with an acute onset, affecting the bone marrow and the peripheral blood. "Moreover, in acute leukemia, high ATG10 expression is significantly associated with elevated white blood cell counts." (PMID 40313244, 2025).
autism (1 paper, 2024). Persistent deficits in social interaction and communication and interaction as well as a markedly restricted repertoire of activity and interest as well as repetitive patterns of behavior. "The important autophagy ATG10 protein is down-regulated in models of autism, and basal neuron autophagy is deficient, impairing normal spinal cord pruning and social behavior during development." (PMID 39038939, 2024).
colon adenocarcinoma (1 paper, 2024). "We analyzed the correlation between KRAS mutational status and expression of several autophagy genes, including MAP1LC3B, ATG5, ATG10, ATG13, and ATG14 in both COAD (colon adenocarcinoma) READ (rectum adenocarcinoma) as well as normal tissue." (PMID 39057088, 2024).
dermatitis (1 paper, 2023). An inflammatory process affecting the skin. "Other cell signaling pathways including cell cycle and NF-kB pathway (CCND1), autophagy (ATG16L2, ATG10), wnt/β-catenin (APC, GSK3β) and angiogenesis (EDN1) regulating genes were associated with RT related acute mucositis and dermatitis." (PMID 37954025, 2023).
diffuse gastric adenocarcinoma (1 paper, 2021). An adenocarcinoma arising from the stomach. "Four DEGs including ATG10, ATG16L2, ULK4 and GABARAPL1 showed differences in diffuse gastric adenocarcinoma subgroup, while other four DEGs including ATG7 (probe 224025_s_at), GABARAPL1, WIPI2 and GABARAPL3 showed differences in gastric intestinal type adenocarcinoma subgroup." (PMID 33604190, 2021).
endotoxemia (1 paper, 2023). "In this study, we provided multiple lines of evidence that HSF1 attenuated the release of inflammatory cytokines in endotoxemia mice by upregulating Atg10." (PMID 36598250, 2023). "In order to determine whether HSF1-mediated protective autophagy and protective effect are related to Atg10 in endotoxemia, cotransfection of pcDNA3.1-HSF1 with siRNA-ATG10 or siRNA-HSF1 with pcDNA3.1-ATG10 was performed in RAW264.7 cells." (PMID 36598250, 2023). "Thus, HSF1-induced protection from endotoxemia was largely Atg10 dependent." (PMID 36598250, 2023). "However, the role of ATG10 in endotoxemia has not been studied." (PMID 36598250, 2023).
enteritis (1 paper, 2021). Inflammation of the small intestine. "In an experiment carried out on rats in which enteritis was induced by intravenous administration of LPS, the transcriptomic analysis showed that the consumption of oat beta-glucans with feed increased the expression of the Atg10 gene belonging to the ATG (autophagy-related genes) family." (PMID 33499397, 2021).
glioblastoma (1 paper, 2022). The most malignant astrocytic tumor (WHO grade IV). "In addition, the relationship between the different clinical features listed in glioblastoma patients and candidate gene polymorphisms was also investigated, finding that ATG10 rs1864183 might be a promising prognosis factor for this tumor." (PMID 35123435, 2022). "Interestingly, we found that TT genotype is associated to shorter overall survival times in glioblastoma patients, suggesting that ATG10 rs1864183 might be related to the prognosis of glioblastoma patients." (PMID 35123435, 2022). "Here, we aimed to assess the potential association between several candidate polymorphisms in autophagy genes (ATG2B rs3759601, ATG16L1 rs2241880, ATG10 rs1864183, ATG5 rs2245214, NOD2 rs2066844 and rs2066845) and glioblastoma susceptibility." (PMID 35123435, 2022). "Our results showed a significant correlation between ATG2B rs3759601, ATG10 rs1864183 and NOD2 rs2066844 variants and higher risk to suffer glioblastoma." (PMID 35123435, 2022). "In this study, we have analyzed common polymorphisms in genes involved in autophagy (ATG2B rs3759601, ATG16L1 rs2241880, ATG10 rs1864183, ATG5 rs2245214, NOD2 rs2066844 and rs2066845) in order to evaluate their role in the susceptibility to suffer glioblastoma." (PMID 35123435, 2022). "However, significant association with glioblastoma risk was found in ATG2B rs3759601, ATG10 rs1864183 and NOD2 rs2066844." (PMID 35123435, 2022). "In addition, Kaplan–Meier analysis showed that patients carrying the TT genotype for ATG10 rs1864183 presented shorter survivals, suggesting that ATG10 rs1864183 might be related to the prognosis of glioblastoma patients." (PMID 35123435, 2022).
Hemoptysis (1 paper, 2022). Coughing up (expectoration) of blood or blood-streaked sputum from the larynx, trachea, bronchi, or lungs. "Our research results also showed that the distribution of ATG10 rs1864182 and rs1864183 genotypes in the subgroups of hemoptysis was statistically significant difference." (PMID 34961976, 2022).
kidney damage (1 paper, 2022). "Therefore, we speculate that ATG10 gene may affect the expression of IL‐8 and cause kidney damage, following hematuria, proteinuria, and other clinical manifestations." (PMID 34961976, 2022).
liver cancer (1 paper, 2025). An epithelial or non-epithelial malignant neoplasm that arises from the liver. "Specifically, the C allele is associated with enhanced luciferase activity and increased gene expression in both HCC and normal hepatic tissues, highlighting ATG-10 rs10514231 as a potential prognostic marker for liver cancer." (PMID 39921803, 2025).
rosacea (1 paper, 2023). A chronic erythematous skin disorder that affects the face. "In the present study, we found that the mRNA expression of autophagy-related genes Becn1, Atg5, Atg10, and Atg12 was significantly increased in LL37-induced rosacea lesions after topical rapamycin treatment." (PMID 36937834, 2023). "The expression of autophagy-related genes (ATG9A, ATG10, ATG12, and PIK3C3) was evidently decreased in rosacea lesions compared with normal skin tissues in the GSE65914 dataset." (PMID 36937834, 2023).
serous ovarian cancer (1 paper, 2022). "Collectively, these findings suggest that Linc00261, a mediator of EMT progression, can target oncogenic miR-552, elevating ATG10 expression, to prevent high-grade serous ovarian cancer tumorigenesis and may serve as a potential novel therapeutic target." (PMID 35465017, 2022).
tumor (29 papers, 2012 to 2025). "Immunohistochemical analysis with clinicopathological features indicated a strong association of the up-regulation of ATG10 with tumor lymph node metastasis (p = 0.005) and invasion (p<0.001)." (PMID 23285162, 2012). "Results of the immunohistochemical analysis showed that ATG10 is closely associated with tumor invasion, which is known risk factor for recurrence and survival outcomes." (PMID 23285162, 2012). "Previous studies have identified that ATG10 was associated with autophagy, immune response, and tumor metastasis in HCC, which suggested that UPS-related genes might contribute to HCC development through regulating biological process." (PMID 37180696, 2023). "Furthermore, ATG10 expression was strongly associated with tumor invasion and metastasis." (PMID 23285162, 2012). "Mechanistic studies suggest that ATG10 contributes to tumor development by regulating cell cycle-related proteins, epithelial-mesenchymal transition and interactions with miRNAs." (PMID 40313244, 2025). "Functionally, ATG10 promotes cancer cell proliferation, migration and invasion, underscoring its potential as a tumor biomarker." (PMID 40313244, 2025). "The expressions of ATG10 in tumor tissues was also higher than that in normal tissues (P < 0.05), and it was extremely highly expressed in ES cell lines." (PMID 35902797, 2022). "In the detection of NPC cell viability, migration and apoptosis ability, it was found that overexpression of ATG10 can effectively interfere with the tumor cell process regulated by miR-100-3p." (PMID 34980191, 2022). "In contrast, ATG10 was upregulated in CRC tissues and increased protein expression of ATG10 was accompanied by tumor lymph node metastasis and invasion." (PMID 36160153, 2022). "Given that ATG10 is an autophagy related gene and plays a tumor suppressive role through restraining the epithelial-mesenchymal transition (EMT) process." (PMID 35465017, 2022). "We conclude that single copies of the ATG7, BECN1, LC3, and ATG10 gene are largely sufficient to sustain autophagy and maintain tumor cell proliferation under treatment with 2DG and DCA." (PMID 35681458, 2022). "As other examples, PTBP1 RNA binding protein that associated with tumor metastasis in CRC tissues directly interacts with autophagy gene ATG10 and regulates ATG10 expression level." (PMID 32265986, 2020). "To examine Sox2, ATG10 and ATG8b protein levels in tumor tissues, we conducted an immunofluorescence assay by confocal microscope using Sox2, ATG10 and ATG8b antibodies." (PMID 23451179, 2013). "In this study, we provided evidence showing that Sox2 induced autophagy through the up-regulation of ATG10 gene expression and cellular senescence, resulting in inhibition of tumor growth ex vivo and in vivo." (PMID 23451179, 2013). "Consistent with the results obtained using tumor tissues, ATG10 expression was higher in cancer cell lines including AMC5, LoVo, SW480, SW48, HCT15, DLD1, RKO and CaCo2 than in the CCD841 normal colorectal cell line." (PMID 23285162, 2012). "We first investigated whether BECN1, LC3, and ATG10 are essential for maintaining tumor cell proliferation under metabolic stress, similar to what has been reported for ATG7." (PMID 35681458, 2022). "In addition, we describe for the first time ATG10 rs1864183 as a putative promising prognosis factor for this tumor." (PMID 35123435, 2022). "In addition, we confirmed that ZFAS1 can regulate the autophagy level of NPC cells through the PI3K/AKT pathway through miR-100-3p/ATG10 to affect tumor progression." (PMID 34980191, 2022). "Further studies showed that ATG10 could promote tumor cells proliferation and malignant transformation." (PMID 32104496, 2020). "Furthermore, the tumor tissues formed from HCT116 cells infected with Sox2 exhibited higher ATG10 and ATG8b protein levels compared with tumors from the HCT116 cells infected with mock vector." (PMID 23451179, 2013).
tumor (continued). "Here, we provide evidence showing that expression of Sox2 in cancer cells induces autophagy of cancer cells by up-regulating ATG10 gene expression and inducing cellular senescence, resulting in reduced malignancy of cancer cells and inhibition of tumor growth ex vivo and in vivo." (PMID 23451179, 2013). "Thirty of the 127 tumor specimens (24%) showed ATG10 expression." (PMID 23285162, 2012). "We further investigated the role of ATG10 in tumor progression and invasion." (PMID 23285162, 2012). "From 1895 metastasis-related genes, they found that the expression of SLC2A1, CDCA8, ATG10, and HOXD9 was higher in HCC tumor tissue whereas the expression of TPM1 was lower." (PMID 37974228, 2023). "Here, we used CRISPR/Cas9 technology to engineer tumor cells with various deletions of the ATGs, which are most frequently hit by SCNAs: BECN1, MAP1LC3B/LC3, and ATG10." (PMID 35681458, 2022). "We screened the genes ATG10 and ATG5 related to autophagy enrichment for further testing and found that only ATG10 was significantly up-regulated in NPC cells and tumor tissues (all p < 0.05)." (PMID 34980191, 2022). "In this study, we report Linc00261, which is a tumor suppressor, inhibits HGSOC progression by competitively binding miR-552, elevating ATG10 expression, and then restrain EMT phenotype." (PMID 35465017, 2022). "The results showed that mRNA levels of ATG10, IL18RAP, PRKCD, SLC11A1, and SPP1 differed between tumor tissues and normal tissues in most of the 33 cancer types." (PMID 34631695, 2021). "Compared with the normal samples, ATG10, PRKCD, and SPP1 were highly expressed in the tumor samples." (PMID 34631695, 2021). "The expression levels of SLC2A1, CDCA8, ATG10 and HOXD9 are higher in tumor samples and lower in normal tissue samples." (PMID 34116652, 2021). "And it was reported that lncRNA ZNFX1 antisense RNA 1 (ZFAS1) could regulate the autophagy level of NPC cells through the miR-100/autophagy related 10 (ATG10) axis and the PI3K/AKT/mTOR pathway to affect tumor progression." (PMID 37069649, 2023). "Comparing to normal group, ATG2B, ATG10, DAPK1 were all high expressed in tumor and cell lines." (PMID 35902797, 2022). "Regarding tumor cell survival, the resistance to metabolic stress induced by TMEM74 overexpression was counteracted by ATG5, ATG7, ATG16L1, ATG3 and ATG10 deficiencies but not the BECN1 and ULK1." (PMID 29048433, 2017). "Cell proliferation and tumor growth were not significantly influenced by ectopic expression of ATG10 (data not shown)." (PMID 23285162, 2012). "We conclude that tumor cell proliferation under metabolic drug treatment is not only dependent on ATG7, but also to an equal extent on BECN1, LC3, and ATG10." (PMID 35681458, 2022). "Western blot analysis of tumor tissues showed no significant changes in c-MYC protein levels but revealed reduced PTBP1 protein and c-MYC S62 phosphorylation levels, along with increased levels of Atg10, Beclin-1, P62, and LC3B." (PMID 40469179, 2025).
cancer (21 papers, 2012 to 2025). A tumor composed of atypical neoplastic, often pleomorphic cells that invade other tissues. "Overexpression of ATG10 is associated with poor prognosis and clinical features in patients with cancer." (PMID 40313244, 2025). "Both in vitro and in vivo studies indicate that ATG10 functions as an oncogenic factor in cancer progression." (PMID 40313244, 2025). "In summary, ATG10 exhibits significant biological functions in cancer progression and holds promise as a novel therapeutic target." (PMID 40313244, 2025). "This review summarizes the molecular mechanisms and clinical significance of ATG10 across cancers, drawing on findings from clinical tissue samples, in vitro experiments and in vivo models." (PMID 40313244, 2025). "As a potential therapeutic target, ATG10 has garnered increasing attention, with ongoing research exploring the effects of its inhibition on cancer treatment." (PMID 40313244, 2025). "ATG10 promotes cancer growth and metastasis by modulating epithelial-mesenchymal transition and cell cycle regulators such as cyclin B1, CDK1 and CDK2." (PMID 40313244, 2025). "This review explores the functional and clinical significance of ATG10 across various cancers, highlighting its potential as a biomarker and therapeutic target." (PMID 40313244, 2025). "The study we conducted expands upon existing findings by illustrating that ATG-10 influences cancer growth and is crucial in forecasting therapeutic outcomes for patients undergoing Sorafenib treatment." (PMID 39921803, 2025). "In both the control and cancer patients, there were positive correlations (p < 0.0001) between KRAS mutational status and the expression of MAP1LC3B, ATG5, ATG10, ATG13, and ATG14." (PMID 39057088, 2024). "Collectively, these findings manifest that compartment switching induced by Arid1a depletion modulates the transcription of some cancer-related genes, such as Pmp22, Atg10, Gsc, Rnf125, and Cdh5, which have been known to be involved in tumorigenesis." (PMID 34689165, 2021). "In our study, expression of ATG12 and ATG7 showed up-regulation while ATG10 expression was down regulated in cancer tissues." (PMID 33604190, 2021). "Specifically, genes such as ATG16L1, ATG5, ATG10 or ATG7, accumulate multiple SNPs linked to pathologies that include cancer, neurological disorders, or inflammatory bowel diseases." (PMID 33147747, 2020). "Autophagy related 10 (ATG10) is a critical gene for autophagy and cancer, and there is increasing evidence for the importance of autophagy-related genes in the maintenance, therapy, and pathogenesis of cancer." (PMID 33095808, 2020). "We also evaluated the effect of ATG10 over-expression on cell proliferation and in a mouse xenograft model using RKO carcinoma cells stably expressing ATG10." (PMID 23285162, 2012). "ATG10 overexpression has been shown to promote cancer metastasis in vitro." (PMID 40313244, 2025). "While preliminary mechanistic insights have been gained, the functional specificity of ATG10 across different cancer types remains unclear." (PMID 40313244, 2025). "ATG10 promotes cancer growth and metastasis through multiple signaling pathways." (PMID 40313244, 2025). "Moreover, in cancer tissues and cells, there is a significant trend of increased ATG10 expression levels." (PMID 40313244, 2025). "Moreover, our results demonstrate that genetic variations in ATG-10 markedly affected treatment outcomes, reinforcing its role in autophagy regulation and cancer therapy resistance." (PMID 39921803, 2025). "Overexpression of miR-369-3p inhibits cancer cell proliferation by targeting ATG10." (PMID 31337985, 2019). "However, the relationship between ATG10 expression and clinical outcomes should be confirmed with a larger cohort to better understand the role of ATG10 in cancer." (PMID 23285162, 2012). "Although the roles of a few ATG proteins in cancer have been characterized, the role of ATG10 is almost completely unknown." (PMID 23285162, 2012).